PVT1 (Pvt1 oncogene)
Diseases named in the same sentence as PVT1 in open-access papers (continued):
Sharing a sentence is not in itself a finding about the gene and the disease.
osteosarcoma (76 papers, 2016 to 2025). A usually aggressive malignant bone-forming mesenchymal neoplasm, predominantly affecting adolescents and young adults. "LncRNA plasmacytoma variant translocation gene 1 (PVT1) promotes epithelial‐mesenchymal transition, proliferation, migration, and invasion of osteosarcoma cells." (PMID 32960485, 2021). "Silencing of lncRNA PVT1 affected the expression of EMT‐associated molecules in osteosarcoma MG‐63 and SW1353 cells." (PMID 32960485, 2021). "In the current study, our aim was to explore the role of lncRNA plasmacytoma variant translocation gene 1 (PVT1) in osteosarcoma." (PMID 32960485, 2021). "Multivariate regression analysis revealed that high expression of lncRNA PVT1 was an independent risk factor for the prognosis of patients with osteosarcoma." (PMID 32960485, 2021). "Similar to its effect in GBC, PVT1 upregulation has been observed in osteosarcoma where it is associated with a poor survival of patients (p = 0.011)." (PMID 33652661, 2021). "The survival analysis revealed that high lncRNA PVT1 expression was associated with poorer prognosis of osteosarcoma." (PMID 32960485, 2021). "Herein, we reported another significantly upregulated circRNA, also encoded by PVT1, circ0085539, in osteosarcoma." (PMID 32983961, 2020). "Furthermore, high expression of lncRNA PVT1 can be utilized as an independent prognostic risk indicator for osteosarcoma." (PMID 32960485, 2021). "The plasmacytoma variant translocation 1 (PVT1) was over-expressed in human osteosarcoma tissue." (PMID 28353666, 2017). "Concurrently, PVT1 was associated with reduced survival in osteosarcoma patients." (PMID 27813492, 2016). "Taken together, this ALKBH5/PVT1/miR-486/PKC-δ axis significantly induced the malignant progression of osteosarcoma, indicating a novel target in osteosarcoma detection and treatment." (PMID 37069649, 2023). "PVT1 had a pivotal role in the GEM resistance of osteosarcoma cells through miR-152 targeting to regulate the c-MET/PI3K pathway." (PMID 37580768, 2023). "PVT1 activated the PI3K/AKT pathway via c-MET to increase the chemotherapy resistance of osteosarcoma cells." (PMID 37580768, 2023). "BMSC-derived exosomes, which express the lncRNA PVT1 in abundance, promoted osteosarcoma growth and metastasis by regulating the miR-183-5p/ERG axis." (PMID 37377390, 2023). "ALKBH5 can mediate m6A demethylation of lncRNA PVT1 in osteosarcoma, thus upregulating PVT1 and promoting osteosarcoma cell proliferation." (PMID 37151887, 2023). "Upregulated PVT1 then promoted osteosarcoma metastasis via a miR-486/protein kinase C delta S homeolog PKC-δ axis." (PMID 37069649, 2023). "A recent study reported that ALKBH5 mediates the m6A modification of PVT1 and increases the stability of PVT1 to promote osteosarcoma tumorigenesis." (PMID 36376862, 2022). "Recently, Chen et al25 revealed that ALKBH5‐mediated m6A modification of lncRNA PVT1 is involved in the occurrence of osteosarcoma." (PMID 32960485, 2021). "The effect of lncRNA PVT1 knockdown on the migration of osteosarcoma cells was evaluated by wound healing assay." (PMID 32960485, 2021). "The findings of this study suggest that lncRNA PVT1 is a potential therapeutic target for osteosarcoma." (PMID 32960485, 2021). "The osteosarcoma cell lines exhibited higher lncRNA PVT1 expression than the normal osteoblast cell line hFOB1.19." (PMID 32960485, 2021). "The effect of lncRNA PVT1 knockdown on the migration and invasion of osteosarcoma cells was evaluated by the Transwell assay." (PMID 32960485, 2021). "Glucose uptake, lactate production and the expression of HK2 are all increased in osteosarcoma cells with an overexpression of PVT1 and decreased by PVT1 knockdown." (PMID 33652661, 2021). "In vitro knockdown of lncRNA PVT1 inhibited the proliferation, migration, and invasion ability of osteosarcoma cells." (PMID 32960485, 2021).
osteosarcoma (continued). "Sun et al24 demonstrated that lncRNA PVT1 is involved in the resistance of osteosarcoma cells through activation of the c‐MET/PI3K/AKT pathway." (PMID 32960485, 2021). "The role of lncRNA PVT1 in osteosarcoma cells was analyzed in vitro using the MG‐63 and SW1353 cell lines." (PMID 32960485, 2021). "The relationship between lncRNA PVT1 expression status and the prognosis of patients with osteosarcoma was analyzed." (PMID 32960485, 2021). "The effect of lncRNA PVT1 knockdown on the proliferation of osteosarcoma cells was evaluated by CCK‐8 assay." (PMID 32960485, 2021). "Song et al23 reported that lncRNA PVT1 is also involved in glucose metabolism and proliferation of osteosarcoma cells through the miR‐497/HK2 pathway." (PMID 32960485, 2021). "The enhanced expression of lncRNA PVT1 was strongly correlated with the degree of tumor differentiation, distant metastasis, and disease stage in patients with osteosarcoma (P < .05)." (PMID 32960485, 2021). "The osteosarcoma tissues exhibited significantly higher lncRNA PVT1 expression than that of the adjacent non‐tumorous tissues." (PMID 32960485, 2021). "This study demonstrated the upregulation of lncRNA PVT1 expression in osteosarcoma cells and tissues and that lncRNA PVT1 is a potential therapeutic target for osteosarcoma." (PMID 32960485, 2021). "The knockdown of lncRNA PVT1 significantly inhibited the migration and invasion abilities of osteosarcoma cells." (PMID 32960485, 2021). "In osteosarcoma cells, ALKBH5-mediated mA modification of PVT1 contributes to osteosarcoma tumorigenesis." (PMID 33955330, 2021). "Knockdown of lncRNA PVT1 expression suppressed the invasion, migration, and proliferation of osteosarcoma cells." (PMID 32960485, 2021). "The expression of lncRNA PVT1 was analyzed in 78 pairs of osteosarcoma tissues and adjacent non‐tumorous tissues." (PMID 32960485, 2021). "Quantitative real‐time reverse transcription‐polymerase chain reaction was used to detect the expression of lncRNA PVT1 in osteosarcoma tissues and cells." (PMID 32960485, 2021). "The GEPIA online analysis revealed that the osteosarcoma samples exhibited significantly higher expression of lncRNA PVT1 than that of the normal samples." (PMID 32960485, 2021). "For example, the circRNA PVT1 facilitates osteosarcoma metastasis through regulation of the miR-526b/FOXC2 axis, and circRNA-33186 participated in the pathogenesis of osteoarthritis through functioning as a sponge of miR-127-5p." (PMID 33506021, 2021). "Cox regression analysis model was constructed to examine the effect of lncRNA PVT1 on the prognosis of patients with osteosarcoma." (PMID 32960485, 2021). "The effect of lncRNA PVT1 on the malignant biological behavior of osteosarcoma cells in vitro was also analyzed." (PMID 32960485, 2021). "For example, mesenchymal transition was reinforced by CRNDE via the Wnt/β-catenin pathway in osteosarcoma, and lncRNA PVT1 sponged miR-195 to enhance EMT and induce therapeutic resistance in cervical cancer." (PMID 33028341, 2020). "LncRNA PVT1 targets miR-152 and enhances the resistance of osteosarcoma to gemcitabine by activating the c-MET/PI3K/AKT pathway." (PMID 32202509, 2020). "EV-associated PVT1 increased/stabilized the expression of oncogenic protein ERG, which correlated to increased proliferation and migration of osteosarcoma cells in vitro and promoted tumor growth and metastasis in vivo." (PMID 32587858, 2020). "Given that the PVT1 in BMSC-EXO increased ERG protein expression via inhibiting ubiquitination and sponging miR-183-5p, we investigated the mechanism of PVT1 on osteosarcoma cell proliferation and migration." (PMID 31699956, 2019). "Meanwhile, the co-transfection of si-PVT1 and miR-183-5p inhibitor restored the ERG protein expression which was reduced by interfering PVT1 in three osteosarcoma cell lines." (PMID 31699956, 2019).
osteosarcoma (continued). "The co-culture with increasing amounts of BMSC-EXO (from 0 to 40 μg/mL) gradually raised the PVT1 levels in osteosarcoma cells." (PMID 31699956, 2019). "Meanwhile, the BMSC-derived exosomes promote osteosarcoma growth and metastasis via PVT1/ERG pathway." (PMID 31699956, 2019). "PVT1 in human is a competitive endogenous lncRNA by acting as a sponge of MIR-195 in osteosarcoma cells." (PMID 31752679, 2019). "Meanwhile, we downregulated the expression of PVT1 in exosomes by interfering PVT1 in BMSCs, the PVT1 expression in osteosarcoma cells showed a reduction after co-culturing with BMSC-EXOsi-PVT1." (PMID 31699956, 2019). "We then overexpressed PVT1 in three osteosarcoma cell lines, and immunoblotted Ub-ERG using ubiquitination assay." (PMID 31699956, 2019). "Herein, the high expression of PVT1 in BMSC-derived exosomes was identified, and the upregulation of PVT1 in osteosarcoma cells was confirmed to be transported from BMSC-derived exosomes." (PMID 31699956, 2019). "Meanwhile, the interference of PVT1 in osteosarcoma cells dramatically increased miR-183-5p expression." (PMID 31699956, 2019). "Taken together, these data indicated that PVT1 in BMSC-EXO promotes osteosarcoma growth and metastasis via increasing ERG." (PMID 31699956, 2019). "In conclusion, our findings indicated that BMSC-derived exosomes promote osteosarcoma growth and metastasis through transporting lncRNA PVT1 to osteosarcoma cells." (PMID 31699956, 2019). "The PVT1 expression in BMSC-derived exosomes was markedly higher than that in osteosarcoma cell-derived exosomes." (PMID 31699956, 2019). "As Ets-1 is a well-defined pro-metastatic factor in osteosarcoma, we supposed that the pro-metastatic effect of PVT1 in BMSC-EXO was exerted via specifically raising ERG expression." (PMID 31699956, 2019). "The co-culturing of BMSC-derived exosomes and osteosarcoma cells (Saos-2, MG-63, and MNNG/HOS cell lines) significantly raised PVT1 expression of osteosarcoma cells." (PMID 31699956, 2019). "After the co-culture with 40 μg/mL BMSC-EXO, the PVT1 expression in osteosarcoma cells was markedly increased compared with the co-culture with MNNG-EXO." (PMID 31699956, 2019). "LncRNA PVT1 promotes glucose metabolism in osteosarcoma by inhibiting miR-497/HK2 signaling through a competing endogenous RNA (ceRNA) mechanism." (PMID 30134946, 2018). "For instance, cessation of PVT1 inhibited osteosarcoma cell proliferation and migration by targeting miR-195, implying a therapeutic target against osteosarcoma." (PMID 30126849, 2018). "The lncRNA PVT1 has been reported to be overexpressed in osteosarcoma and to promote migration and invasion through regulating the miR-195/FASN pathway." (PMID 30134946, 2018). "Inhibiting PVT1 reduced miR-195 activity and subsequently depressed osteosarcoma cell ability for migration and invasion." (PMID 28353666, 2017). "For instance, in osteosarcoma pathogenesis, lncRNA PVT1 promotes osteosarcoma progression by acting as miR-195 sponge to regulate cell cycle arrest and apoptosis via miR-195 in osteosarcoma cells." (PMID 29262629, 2017). "Nine different long non-coding RNAs were studied in these 10 included articles, with 7 lncRNAs including MALAT1, BCAR4, FGFR3-AS1, HOTAIR, TUG1, FOXC2-AS1 and PVT1 were up-regulated in osteosarcoma cells or patients." (PMID 29245999, 2017). "Specifically, the current study indicates the effects of PVT1 in osteosarcoma, the functional mechanisms of the interaction between PVT1 and miRNAs, and the roles of potential downstream genes." (PMID 27813492, 2016). "In summary, our results indicated that lncRNA PVT1 was overexpressed in osteosarcoma and decreased the survival rate of osteosarcoma patients." (PMID 27813492, 2016). "Simultaneously, we found that silencing PVT1 by siRNA suppressed proliferation, migration and invasion and promoted cell cycle arrest and apoptosis via miR-195 in osteosarcoma cells." (PMID 27813492, 2016).
osteosarcoma (continued). "In this study, the qRT-PCR results indicated that the lncRNA PVT1 is overexpressed in osteosarcoma and decreased the survival rate of osteosarcoma patients." (PMID 27813492, 2016). "We also studied the impact of silencing PVT1 on the proliferation and apoptosis of osteosarcoma cells." (PMID 27813492, 2016). "The results revealed that silencing PVT1 by siRNA inhibited proliferation, migration and invasion and promoted apoptosis and cell cycle arrest in osteosarcoma cells." (PMID 27813492, 2016). "We also proved that PVT1 expression was higher in metastatic osteosarcoma tissues than in primary osteosarcoma tissues." (PMID 27813492, 2016). "We further investigated the role of miR-195 in the influence of PVT1 expression on the proliferation, cell cycle, apoptosis, migration and invasion of osteosarcoma cells." (PMID 27813492, 2016). "We also studied the impacts of silencing PVT1 on the migration, invasion and cell cycle of osteosarcoma cells." (PMID 27813492, 2016). "We then found that PVT1 negatively regulated miR-195 in osteosarcoma cells, and silencing PVT1 suppressed proliferation, migration and invasion and promoted cell cycle arrest and apoptosis via miR-195 in osteosarcoma cells." (PMID 27813492, 2016). "Some of these genes, or the pathways they regulate, including the PVT1/MYC locus, MET signaling, and IGF1R have been implicated in genetically engineered mouse models of osteosarcoma." (PMID 29056713, 2016). "Similarly, the m6A demethylation of lncRNA PVT1 by ALKBH5 promotes the development of osteosarcoma, highlighting the importance of chromatin modifiers in regulating m6A gene expression." (PMID 40225569, 2025). "In osteosarcoma, TRIM28 promotes the SUMOylation modification of VPS34 by forming a complex with PVT-1 (Plasmacytoma variant translocation-1), further enhancing the ubiquitination and degradation of TSC2, thereby enhancing the self-renewal and stem cell phenotype of osteosarcoma cells." (PMID 39100077, 2024). "It has been found that PVT1 (plasmacytoma variant translocation 1) could promote human OS malignant biological behaviors, but the role of PRR7-AS1 in osteosarcoma remains unknown." (PMID 38033505, 2023). "miR-152 attenuated lncRNA PVT1-induced apoptosis via c-MET/PI3K/AKT pathway in osteosarcoma cell." (PMID 36445489, 2023). "A recent transcriptome profiling study based on the TARGET data detected a total of 13,903 expressed lncRNAs and their integrative gene expressions and SCNA analysis revealed 167 novel driver lncRNAs (including 2 previously reported lncRNA PVT1 and ZFAS1) to be associated with osteosarcoma." (PMID 35755302, 2022). "The key is that BMSCs exosomes can enter osteosarcoma cells with transferring lncRNA PVT1." (PMID 36309693, 2022). "In addition, we confirmed that lncRNA PVT1 affected the epithelial‐mesenchymal transition of osteosarcoma cells." (PMID 32960485, 2021). "However, the role of lncRNA PVT1 in osteosarcoma has been evaluated in only a limited number of studies." (PMID 32960485, 2021). "Here, we investigated the expression and molecular function of lncRNA PVT1 in osteosarcoma." (PMID 32960485, 2021). "The expression of lncRNA PVT1 was also determined in osteosarcoma cell lines." (PMID 32960485, 2021). "In 2017, Zhou et al22 reported that osteosarcoma tissues overexpress lncRNA PVT1 and that silencing lncRNA PVT1 induces cell cycle arrest and apoptosis and suppresses migration, proliferation, and invasion of osteosarcoma cells by exerting a negative regulatory effect on miR‐195." (PMID 32960485, 2021). "Moreover, the lncRNA plasmacytoma variant translocation 1 (PVT1), transported in MSCs-derived EVs, was found to promote proliferation and migration in osteosarcoma cells." (PMID 34198693, 2021). "High lncRNA PVT1 expression indicated poor prognosis in patients with osteosarcoma." (PMID 32960485, 2021).
osteosarcoma (continued). "Further, evidence confirms that potential prognostic markers also exist in other cancers, such as LINC01234 in NSCLC, miR-744-5p in ovarian cancer, lncRNA LNCAROD in head and neck squamous cell carcinoma, lncRNA PVT1 in osteosarcoma, miR-25-3p and lncRNA DANCR in pancreatic cancer." (PMID 35004679, 2021). "There are limited studies on the role of lncRNA PVT1 in osteosarcoma." (PMID 32960485, 2021). "However, further studies are needed to elucidate the molecular mechanism by which lncRNA PVT1 promotes the progression of osteosarcoma." (PMID 32960485, 2021). "LncRNA PVT1 is a potential therapeutic target for osteosarcoma." (PMID 32960485, 2021). "The expression of lncRNA PVT1 was markedly upregulated in osteosarcoma tissue." (PMID 32960485, 2021). "Interestingly, EVs derived from PVT1 knockdown cells negated these effects, thereby highlighting their potential therapeutic application for osteosarcoma." (PMID 32587858, 2020). "Moreover, PVT1 was encapsulated into bone marrow mesenchymal stem cells (BMSCs)-derived exosomes and promoted osteosarcoma cell proliferation and migration." (PMID 33050642, 2020). "Another investigation revealed that m6A demethylase ALKBH5 could suppress the degradation of lncRNA PVT1, and its overexpression promoted osteosarcoma cell proliferation in vitro and tumor growth in vivo." (PMID 32982586, 2020). "Similar observations were reported for the interaction of miR-195-5p and PVT1 also in osteosarcoma." (PMID 31781490, 2019). "Alternatively, circRNA PVT1 may contribute to doxorubicin and cisplatin resistance in osteosarcoma by regulating multidrug resistance protein 1 (MDR1)." (PMID 31508377, 2019). "In osteosarcoma cells, lncRNA Pvt1 was found to act as a sponge molecule to adsorb miR-195." (PMID 31850189, 2019). "Furthermore, lncRNA PVT1 upregulation can promote the proliferation, migration, and invasion of osteosarcoma by regulating the miR-195/FA synthase (FASN) signaling pathway." (PMID 31757221, 2019). "PVT1 could act as molecular sponge to repress the expression of miR-497 and promote the development of osteosarcoma." (PMID 30083911, 2019). "The direct binding between PVT1 and the oncogenic protein ERG was confirmed using RNA immunoprecipitation and RNA pull-down assays, and the transported PVT1 promotes osteosarcoma cell proliferation and migration via inhibiting degradation and ubiquitination of ERG." (PMID 31699956, 2019). "As reported, PVT1 is up-regulated in various malignant tumors, including osteosarcoma." (PMID 31699956, 2019). "Finally, a recent study identified PVT1 as an important contributor to resistance to gemcitabine, a nucleoside analog currently used for the treatment of osteosarcoma." (PMID 31781490, 2019). "PVT1 is a well-identified oncogenic lncRNA, promoting the progression of numbers of tumor kinds, including non-small-cell lung cancer, gallbladder cancer, and osteosarcoma, and predicting poor overall survival of tumors." (PMID 31699956, 2019). "Finally, PVT1 also functioned as critical regulator in the prognosis of other system tumors, including cervical carcinoma, ovarian cancer and osteosarcoma." (PMID 30083911, 2019). "Moreover, relevant literature confirmed that circ-PVT1 was up-regulated in doxorubicin and cisplatin-resistant osteosarcoma cells and acted as an oncogene to accelerate chemotherapy resistance of osteosarcoma cells." (PMID 31793989, 2019). "We also presented the first study implicating circRNA PVT1 in chemoresistance in osteosarcoma." (PMID 31508377, 2019). "HK2 was a direct target of miR-497, long non-coding RNA PVT1 acts as molecular sponge to repress miR-497, as a result, PVT1 promotes glycolysis and cell proliferation in osteosarcoma and form a PVT1/miR-497 axis in the Warburg effect through regulation of HK2 expression." (PMID 28738810, 2017). "We found that PVT1 negatively regulated miR-195 in osteosarcoma cells." (PMID 27813492, 2016).